GK5 (glycerol kinase 5)
Description:
Skin-specific kinase that plays a key role in glycerol metabolism, catalyzing its phosphorylation to produce sn-glycerol 3-phosphate. Involved in skin-specific regulation of sterol regulatory element-binding protein (SREBP) processing and lipid biosynthesis.
Synonyms: MGC40579
Tractability: PROTAC: ubiquitination databases record sites on it.
Gene: Protein-coding gene on chromosome 3 (142,157,527 to 142,225,592, reverse strand). Ensembl gene ENSG00000175066.
Subcellular location: Cytoplasm
Subcellular location (Human Protein Atlas): Cytosol; Nucleoplasm
Gene Ontology:
Molecular function: glycerol kinase activity; kinase activity; phosphotransferase activity, alcohol group as acceptor
Biological process: glycerol-3-phosphate biosynthetic process; triglyceride metabolic process; carbohydrate metabolic process; glycerol catabolic process
Cellular component: mitochondrion; cytoplasm
Genetic constraint (gnomAD): Loss-of-function variants: 6 observed, 18.38 expected, observed/expected ratio (o/e) 0.33, 90% interval 0.18 to 0.64. The upper end of that interval is the gene's LOEUF score, 0.64, which puts it in group 2 of 6, group 1 being the genes least tolerant of losing a copy. Missense variants: 165 observed, 208.01 expected, observed/expected ratio (o/e) 0.79, 90% interval 0.7 to 0.9. Synonymous variants: 83 observed, 75.1 expected, observed/expected ratio (o/e) 1.11, 90% interval 0.93 to 1.33.
Homologues: Orthologues: chimpanzee GK5 (99% identical), macaque GK5 (97% identical), rabbit GK5 (87% identical), pig GK5 (86% identical), dog GK5 (85% identical), guinea pig GK5 (81% identical), mouse Gk5 (81% identical), rat Gk5 (76% identical), tropical clawed frog gk5 (63% identical), zebrafish gk5 (61% identical), Drosophila melanogaster CG1271 (40% identical), Caenorhabditis elegans C55B6.1 (37% identical). Paralogues in human: GK (32% identical), GK3 (32% identical), GK2 (32% identical), FGGY (20% identical), XYLB (15% identical), SHPK (12% identical).
Diseases named in the same sentence as GK5 in open-access papers:
GK5 is named in the same sentence as 12 diseases in open-access papers, as found by Europe PMC text mining. Sharing a sentence is not in itself a finding about the gene and the disease. The quoted sentences say what the papers report.
lung adenocarcinoma (3 papers, 2019 to 2026). A carcinoma that arises from the lung and is characterized by the presence of malignant glandular epithelial cells. "With respect to GK, cancer tissue expression of GK-5 (both mRNA and protein), as well as elevated exosomal GK-5 mRNA levels in plasma, were reported in patients with gefitinib-resistant compared to gefitinib-sensitive lung adenocarcinoma." (PMID 40927981, 2026). "Real-time PCR and Western blot were used to examine the expression of GK5 mRNA and protein in gefitinib-sensitive and -resistant human lung adenocarcinoma cells." (PMID 30791926, 2019). "The mRNA and protein levels of GK5 were significantly upregulated in gefitinib-resistant human lung adenocarcinoma PC9R and H1975 cells compared with gefitinib-sensitive PC9 cells." (PMID 30791926, 2019).
lung carcinoma (2 papers, 2019 to 2024). "In this study, we showed that GK5 is upregulated in gefitinib-resistant clinical samples and lung cancer cells, and mediates gefitinib resistance." (PMID 30791926, 2019).
diabetes (1 paper, 2024). "Loci for the other genes—PTP4A1, APOBR, BMS1P4-AGAP5, MAPK8IP1P1, GYS2, FAM25C, and GK5–were formerly associated with traits involved with comorbidities of OSA, i.e., BMI, weight, triglycerides, blood pressure, stroke, brain volume, cortical thickness, mood, insulin, and diabetes." (PMID 39457448, 2024).
cancer (4 papers, 2019 to 2026). A tumor composed of atypical neoplastic, often pleomorphic cells that invade other tissues. "GK5 induced drug resistance in gefitinib-sensitive PC9 cells, confirming that GK5 expression is sufficient to induce gefitinib resistance in cancer cells." (PMID 30791926, 2019).
adenocarcinoma (2 papers, 2019 to 2024). A common cancer characterized by the presence of malignant glandular cells. "Here we show that exosomal GK5 mRNA in the plasma from gefitinib-resistant adenocarcinoma patients was significantly higher compared to gefitinib-sensitive patients." (PMID 30791926, 2019). "We found that the exosomal mRNA of GK5 in the plasma of patients with gefitinib-resistant adenocarcinoma was significantly higher compared with that of gefitinib-sensitive patients." (PMID 30791926, 2019).
GK5 also shares sentences with these, for which no sentence is quoted: tumor (4 papers); alopecia (1); colorectal carcinoma (1); Hepatic steatosis (1); hepatocellular carcinoma (1); non-small cell lung carcinoma (1); Stroke (1).